Y_RNA (Y RNA )
Gene: Miscellaneous RNA gene on chromosome 1 (236,060,677 to 236,060,772, forward strand). Ensembl gene ENSG00000252822.
Homologues: Orthologues: chimpanzee Y_RNA (99% identical). Paralogues in human: RNY4P7 (84% identical), RNY4 (83% identical), RNY4P10 (83% identical), RNY4P6 (82% identical), Y_RNA (82% identical), RNY4P14 (81% identical), RNY4P25 (81% identical), Y_RNA (81% identical), RNY4P3 (80% identical), Y_RNA (80% identical), RNY4P24 (79% identical), RNY4P37 (79% identical), and 87 more.